TRPC7 (transient receptor potential cation channel subfamily C member 7)
Description:
Non-selective, calcium-permeable cation channel. Also transports maganese. Contributes to both spontaneous and receptor stimulation-induced cationic currents. Receptor stimulation, including that of G(q)-coupled or receptor tyrosine kinase pathways, triggers phospholipase C (PLC)-mediated hydrolysis of phosphatidylinositides, producing diacylglycerol (DAG) that activates TRPC7. May also be activated by depletion of intracellular calcium stores. Mediates depolarization of intrinsically photosensitive retinal ganglion cells (ipRGCs) in response to light-induced melanopsin (OPN4)-mediated phototransduction via G(q)-PLC signaling, likely by forming heteromeric TRPC6-TRPC7 channels.
Synonyms: TRP7
Tractability: Small molecule: a high-quality ligand is known; it belongs to a druggable protein family. Antibody: UniProt places it where antibodies can reach, with high confidence; its Gene Ontology location is reachable by antibodies, with high confidence; UniProt predicts a signal peptide or a membrane-spanning region. PROTAC: its protein half-life has been measured; a small molecule that binds it is known.
Target class: Voltage-gated ion channel; Ion channel; Transient receptor potential channel
Gene: Protein-coding gene on chromosome 5 (136,212,745 to 136,365,545, reverse strand). Ensembl gene ENSG00000069018.
Subcellular location: Cell membrane; Nucleus envelope
Pathways (Reactome):
Hemostasis: Effects of PIP2 hydrolysis; Elevation of cytosolic Ca2+ levels
Developmental Biology: Role of second messengers in netrin-1 signaling
Transport of small molecules: TRP channels
Gene Ontology:
Molecular function: protein binding; calcium channel activity; inositol 1,4,5 trisphosphate binding; store-operated calcium channel activity
Biological process: calcium ion transmembrane transport; regulation of cytosolic calcium ion concentration; single fertilization
Cellular component: cation channel complex; plasma membrane; membrane; nuclear envelope; perinuclear region of cytoplasm
Genetic constraint (gnomAD): Loss-of-function variants: 42 observed, 91.13 expected, observed/expected ratio (o/e) 0.46, 90% interval 0.36 to 0.6. The upper end of that interval is the gene's LOEUF score, 0.6, which puts it in group 2 of 6, group 1 being the genes least tolerant of losing a copy. Missense variants: 955 observed, 1,149.9 expected, observed/expected ratio (o/e) 0.83, 90% interval 0.79 to 0.88. Synonymous variants: 451 observed, 457.5 expected, observed/expected ratio (o/e) 0.99, 90% interval 0.91 to 1.07.
Homologues: Orthologues: chimpanzee TRPC7 (99% identical), macaque TRPC7 (99% identical), guinea pig TRPC7 (99% identical), pig TRPC7 (99% identical), rabbit TRPC7 (99% identical), dog TRPC7 (98% identical), rat Trpc7 (98% identical), mouse Trpc7 (98% identical), zebrafish trpc7a (81% identical), zebrafish trpc7b (73% identical), Caenorhabditis elegans trp-1 (36% identical). Paralogues in human: TRPC3 (79% identical), TRPC6 (74% identical), TRPC4 (38% identical), TRPC5 (37% identical), TRPC1 (31% identical).
Diseases named in the same sentence as TRPC7 in open-access papers:
TRPC7 is named in the same sentence as 22 diseases in open-access papers, as found by Europe PMC text mining. Sharing a sentence is not in itself a finding about the gene and the disease. The quoted sentences say what the papers report.
lung cancer (3 papers, 2013 to 2020). A malignant neoplasm involving the lung. "Furthermore, TRPC7 was found to be overexpressed in tumor biopsies from patients with non‐small cell lung cancer." (PMID 31755176, 2020). "The mRNAs for TRPC5 and TRPC7 were undetectable in normal and lung cancer tissues." (PMID 23840757, 2013).
glioma (1 paper, 2024). A benign or malignant brain and spinal cord tumor that arises from glial cells (astrocytes, oligodendrocytes, ependymal cells). "Expression levels of TRPGs were found to differ significantly between normal and glioma tissues, except for TRPC3 and TRPC7." (PMID 38948951, 2024).
leukemia (1 paper, 2014). A malignant (clonal) hematologic disorder, involving hematopoietic stem cells and characterized by the presence of primitive or atypical myeloid or lymphoid cells in the bone marrow and the blood. "TRPC7 is expressed in the nervous system (dorsal root ganglion cells), keratinocytes, uterine myometrium and in leukemia cells." (PMID 24852263, 2014). "PGE2-induced apoptosis in K562 human leukemia cells is regulated by TRPC7." (PMID 24852263, 2014).
lung adenocarcinoma (1 paper, 2024). A carcinoma that arises from the lung and is characterized by the presence of malignant glandular epithelial cells. "In lung adenocarcinoma patients, overexpression of TRPC7 is associated with poor prognosis and lower survival rates." (PMID 38510751, 2024). "For instance, in a clinical study on lung adenocarcinoma, TRPC7 expression varied among patients." (PMID 38510751, 2024). "Similarly, in one study, TRPC7 knockdown arrested lung adenocarcinoma cells, H1299, at the G0/G1 phase, synchronizing cells to a single phase." (PMID 38510751, 2024).
neuroblastoma (1 paper, 2013). Neuroblastoma (NB) is the most common solid, extracranial childhood tumor. "For example, the expression of TRPC7 is negative in A549 and SKOV-3, but positive in HepG2 cells in this study and in the differentiated neuroblastoma cells." (PMID 23840757, 2013).
nicotine dependence (1 paper, 2009). Physical and psychological dependence on nicotine. "The association of rs7050529 (IVS3+286 of TRPC5) with CPD is notable as a closely related family member, TRPC7, was previously significantly associated with nicotine dependence." (PMID 19247474, 2009).
ovarian carcinoma (1 paper, 2026). A malignant neoplasm originating from the surface ovarian epithelium. "For example, TrpV4, TrpC7, and several TrpM family members (TrpM2, TrpM4, TrpM8) are upregulated in ovarian cancer, where their expression negatively correlates with patient prognosis." (PMID 41557739, 2026).
pancreatic cancer (1 paper, 2022). "Sensory ion channels TRPC3 and TRPC7 could be the potential therapeutic targets in pancreatic cancer and TRPC3 might be involved in dysregulating mitochondrial functions during PAAD genesis." (PMID 35330477, 2022).
papilloma (1 paper, 2020). A benign epithelial neoplasm that projects above the surrounding epithelial surface and consists of villous or arborescent outgrowths of fibrovascular stroma. "We also observed the overexpression of TRPC7 in UVB‐exposed skin, especially in papilloma." (PMID 31755176, 2020).
Pulmonary hemorrhage (1 paper, 2025). Pulmonary hemorrhage is a bleeding within the lungs. "In the lungs, ECSCR, KNG1, PLG, and transient receptor potential (TRP) cation channel subfamily C member 7 (TRPC7) were identified as factors that may contribute to pulmonary hemorrhage through various signaling pathways." (PMID 39764561, 2025).
skin aging (1 paper, 2020). The gradual irreversible changes in structure of skin that occur as a result of the passage of time.. "According to our study, environmental stimulus with UVB activates TRPC7, which is pivotal to the initiation of tumorigenesis associated with skin aging." (PMID 31755176, 2020). "Our discovery that TRPC7 is a nociceptive mechanoreceptor, together with our previous finding that TRPC7 has a role in UVB‐induced skin aging via increased ROS production, is consistent with the previously reported links between nociceptive TRP receptors and aging." (PMID 31755176, 2020). "Next, we examined the mechanism underlying the involvement of TRPC7 in skin aging by testing our hypothesis that TRPC7 initiates UVB‐induced skin aging via [Ca2+]i elevation." (PMID 31755176, 2020). "We first characterized TRPC7 as a nociceptive mechanoreceptor; then, we performed a screen in human keratinocytes to determine that, among other TRP channels, TRPC7 is uniquely involved in UVB‐induced skin aging." (PMID 31755176, 2020).
skin tumour (1 paper, 2021). "TRPC7 was characterized as a nociceptive mechanoreceptor, and it was described to mediate UVB-induced epidermal pathology, epidermal aging, and skin tumour initiation and growth in mice." (PMID 34828338, 2021). "Here, TRPC7 was characterized as a nociceptive mechanoreceptor, and it was described to mediate UVB-induced epidermal pathology, epidermal aging, and skin tumour initiation and growth in mice." (PMID 34828338, 2021).
cancer (9 papers, 2009 to 2025). A tumor composed of atypical neoplastic, often pleomorphic cells that invade other tissues. "In support, GSEA found a prominent cancer hallmark signaling network of RAS signaling to be amongst the most inversely correlated to activation to TRPC7 expression." (PMID 35330477, 2022). "GSEA enrichment revealed the core genes of the signature, TRPC3 and TRPC7, were involved in several cancer-related pathways." (PMID 35330477, 2022). "Although TRPC3 and TRPC7 mediate store-operated Ca2+ entry (SOCE) potentiating acceleration of cancer cell growth, seldom does the study point out the function of TRPC7 in cancer development." (PMID 36045706, 2021). "As both other TRPC subgroup members TRPC3 and TRPC6, TRPC7 is suggested to play a potential role in the physiology and pathology of neurological disorders, in the cardiovascular system, and in cancer cell growth and progression." (PMID 34828338, 2021). "Our analysis of the pathologic features of cancer in human tissues also supported the hypothesis that TRPC7 promotes cancer progression by mediating tumor growth." (PMID 31755176, 2020). "Additionally, investigating whether an association of episodes of pain symptoms of the cancer patients and their relative TRPC3/TRPC7 activation in the tumor tissue exists is desirable." (PMID 35330477, 2022). "Schematic representation of the role of TRPC7 as a potential tumor initiator gene in ultraviolet B (UVB)‐induced aging and cancer progression." (PMID 31755176, 2020). "Two genes (MAGEA12, TRPC7) are up-regulated and one gene (FCGRT) is down-regulated in the metastases from the 4 cancer types with significant gene lists." (PMID 29254233, 2017). "SKF-96365, a non-specific TRPC6 and TRPC7 antagonist, displays cytotoxic effects in several cancer cell types." (PMID 34458247, 2021).
tumor (6 papers, 2020 to 2022). "If Ca2+ entry from TRPC7 is important to maintain tumorigenesis, malignant cells potentiate intensive epigenetic regulation and mutation according to the evolution of a tumor (Coyle, Boudreau, & Marcato, 2017)." (PMID 31755176, 2020). "Our findings support that TRPC7 is a potential tumor initiator gene and that it causes cell aging and genomic instability, followed by a change in the activity of proto‐oncogenes and tumor suppressor genes to promote tumorigenesis." (PMID 31755176, 2020). "TRPC7 expression trend is opposite to TRPC3 revealing higher expression value is higher in adjacent samples than in tumor tissues (p = 4.3 × 10−3)." (PMID 35330477, 2022). "Although the blockage of TRPC7 inhibits tumor initiation, it cannot completely prohibit tumor formation." (PMID 31755176, 2020). "In this study, we show evidence for a role of TRPC7 as a potential tumor initiator gene in UVB‐induced epidermal aging and skin tumorigenesis." (PMID 31755176, 2020). "In our study, we found that TRPC7 upregulation in tumors promotes tumor growth and also maintains genomic instability." (PMID 31755176, 2020). "Notably, among the four genes signature, only the CXCL10 gene was involved in tumor immunity; however, few studies have been conducted in oncology for the other three genes (TRPC7, CUX2, and COL2A1)." (PMID 34276760, 2021). "The function of TRPC7 as a potential tumor initiator gene is supported by our findings that it initiates tumor progression by causing cell aging and genomic instability, followed by a change in the activity of proto‐oncogenes and tumor suppressor genes to promote tumorigenesis." (PMID 31755176, 2020). "Importantly, we show for the first time to our knowledge that TRPC7 plays a critical role in all steps of tumorigenesis, starting with the initiation of tumor formation." (PMID 31755176, 2020). "Significantly fewer TRPC7+/− and TRPC7−/− mice than wild‐type mice developed tumors, and the tumors that did develop in TRPC7+/− and TRPC7−/− mice were of significantly smaller volume, although TRPC7 deficiency did not completely eliminate tumor formation." (PMID 31755176, 2020). "Indeed, our findings suggest that TRPC7 is a potential tumor initiator gene in tumorigenesis." (PMID 31755176, 2020). "Differential expression analysis showed that the expression of TRPC7, TRPV4, and other TRP family members was significantly different between tumor and normal tissues." (PMID 35813831, 2022). "In addition, as we see the correlation of reduced expression of TRPC7 and shortened RFS and a trend to be reduced in the invasive tumor area, it let us speculate that TRPC7 may have tumor-suppressive roles or be an activator regulatory network that diminishes the tumor." (PMID 35330477, 2022). "This conclusion is also applicable for samples with positive TRPC7 mRNA abundancy (89.0%), meaning that in any case of positive signal for TRPC3 or TRPC7 expression in a given tumor, the tumor cells frequently possesses the prominent mTOR pathway activating mutation." (PMID 35330477, 2022). "The remaining three mutations showed a reduced amount; however, they were still detectable to a significant extent: TRPC7-rs566980923 (ID = 1148), 12.5% in tumor and 4.9% in PF; AMPH-COSM1673120 (ID = 2324), 15.1% (tumor) and 4.01% (PF); NLGN1-COSM479730 (ID = 2438), 21.95% and 1.59%, respectively." (PMID 34070018, 2021).
TRPC7 also shares sentences with these, for which no sentence is quoted: autosomal dominant polycystic kidney disease (1 paper); breast carcinoma (1); cardiac diseases (1); colitis (1); Hyperglycemia (1); ischemia (1); Nephropathy (1); neurological disorders (1).